AFG3L2 (AFG3 like matrix AAA peptidase subunit 2)
Diseases named in the same sentence as AFG3L2 in open-access papers (continued):
Sharing a sentence is not in itself a finding about the gene and the disease.
optic atrophy (8 papers, 2015 to 2025). A disorder characterized by loss of optic nerve fibers. "In this patient, we found a variant of the AFG3L2 gene that presumably explains the presence of optic atrophy in a subject affected by CSNB." (PMID 39564550, 2024). "We describe a patient affected by CSNB secondary to the CACNA1F pathogenetic variant who presented a bilateral optic disc atrophy that was found to be related to another variant in AFG3L2 known as associated with hereditary optic neuropathy." (PMID 39564550, 2024). "The variant in AFG3L2 presumably explains the additional and atypical clinical feature of optic atrophy in the clinical phenotype of CSNB." (PMID 39564550, 2024). "Sanger sequencing of AFG3L2 revealed segregation of the variant with optic atrophy in participating individuals and followed an autosomal dominant pattern of inheritance." (PMID 35970831, 2022). "By clinical exome analysis we identified a novel mutation in AFG3L2 (p.G337E) segregating with optic atrophy within the family." (PMID 32600459, 2020). "Clinical exome analysis detected a novel mutation in the AFG3L2 gene (NM_006796.2:c.1010G > A; p.G337E), which segregated with optic atrophy in family members." (PMID 32600459, 2020). "We identified a heterozygous missense mutation NM_006796.2(AFG3L2):c.1010G > A in exon 8 of the AFG3L2 gene in a family member with optic atrophy." (PMID 32600459, 2020). "In this respect, finding novel AFG3L2 mutations related to DOA or disclosing optic atrophy in SCA28 patients would strongly reinforce the data that we presented here." (PMID 26539208, 2015). "Here, we identified a novel mutation c.1402C>T in AFG3L2, modifying the arginine 468 in cysteine in an evolutionary highly conserved arginine-finger motif, in a family with optic atrophy and mild intellectual disability." (PMID 26539208, 2015). "In our patient, the AFG3L2 variant could explain the optic atrophy as the additional pathologic change associated with the CSNB phenotype, giving new insight into the genotypic–phenotypic correlation." (PMID 39564550, 2024). "Thus, our results suggest that neuro-ophthalmological symptom as optic atrophy might be associated with AFG3L2 mutations, and should prompt the screening of this gene in patients with isolated and syndromic inherited optic neuropathies." (PMID 26539208, 2015). "After excluding variants in mitochondrial DNA and other nuclear genes associated with optic atrophy (e.g., OPA1, AFG3L2), the compound heterozygous SPG7 variants p.Val180Met and p.Gly349Ser were identified." (PMID 41149856, 2025). "The large majority of these variants affected the AAA (ATPase) domain, suggesting that the unbalanced processing of OPA1 consequent to AFG3L2 dysfunction possibly leads to the optic atrophy phenotype." (PMID 39564550, 2024). "G337E [c.1010G > A] mutation of AFG3L2 causes aberrant processing of OPA1 and OMA1 leading to optic atrophy." (PMID 38012514, 2024). "Most of the studies imply that AFG3L2 mutations are majorly linked with autosomal dominant SCA28, and some mutations are involved in developing the SPAX5 or SCAR and optic atrophy." (PMID 38012514, 2024). "Yet, optic atrophy is found associated with spastic paraplegia linked to recessive mutations in SPG7, the paralog of AFG3L2 encoding another component of the m-AAA protease involved in OPA1 proteolytic maturation." (PMID 26539208, 2015). "Whether AFG3L2 mutations causing SCA28, SPAX5, or optic atrophy can cause additional risk of PD by generating altered PINK1 cleavage is an intriguing aspect to test." (PMID 38012514, 2024). "In this patient, we suggest that the optic atrophy could be the expression of the mitochondrial impairment AFG3L2." (PMID 39564550, 2024). "Both patients described in this study, who harbored a novel AFG3L2 mutation, had typical signs of hereditary optic atrophy, without abnormal gait or signs of cerebellar impairment." (PMID 26539208, 2015).
optic atrophy (continued). "In addition, genetic analysis of a large family with isolated optic atrophy disclosed the first dominant SPG7 mutation, c.1232A>C, p.D411A, affecting the AAA domain, 56 amino-acids upstream of the conserved RPGR motif, in which we found the AFG3L2 mutation." (PMID 26539208, 2015). "Yet, it is possible that asymptomatic optic atrophy exists in SCA28 and SPAX5 patients since decreased visual acuity can be absent in moderate forms of optic atrophy, suggesting that future patients with AFG3L2 mutations should have systematic fundus and OCT examinations." (PMID 26539208, 2015).
Spastic paraplegia (6 papers, 2010 to 2025). Complete loss of the ability to move the lower limbs accompanied by spasticity of the lower limbs. "Mutations in the mitochondrial m-AAA protease genes cause two different neurodegenerative diseases in humans: loss of function of SPG7 is associated with an autosomal recessive form of spastic paraplegia, whereas missense mutations in AFG3L2 have recently been associated with SCA28." (PMID 20426821, 2010). "Both AFG3L2 and SPG7 are involved in a neurodegenerative disease, namely the autosomal dominant spinocerebellar ataxia SCA28 and a recessive form of spastic paraplegia, respectively." (PMID 20426821, 2010).
optic atrophy 12 (5 papers, 2022 to 2025). "Optic atrophy-12 (OPA12) is an autosomal dominant neurologic disorder caused by AFG3L2 mutation in 18p11.21 location." (PMID 38012514, 2024).
spastic ataxia 5 (5 papers, 2011 to 2025). "Loss of AFG3L2 function is associated with autosomal recessive spastic ataxia 5 (SPAX5) and autosomal dominant spinocerebellar ataxia 28 (SCA28) with myopathy and CPEO." (PMID 38390227, 2023).
optic neuropathies (4 papers, 2015 to 2024). "It clearly summarized 38 AFG3L2 variants in patient cohorts from their own as well as other studies where pathogenic variants related to optic neuropathy were clustered in the ATPase domain affecting either of the functions related with ATP hydrolysis, ATP binding, and substrate interaction." (PMID 38012514, 2024). "Caporali and co-workers performed an exhaustive study on the role of AAAs in optic neuropathy where their studies showed using both yeast and patient fibroblast that AFG3L2 mutations indirectly affect OPA1 processing, resulting in mitochondrial fragmentation not seen in SCA28 patients." (PMID 38012514, 2024). "The genetic analysis demonstrated that the patient harbored a heterozygous missense variant in AFG3L2 Chr18(GRCh37):g.12356821G>A NM_006796.3: c.1036C>T, p.(Leu346Phe), leading to the associated diagnosis of AFG3-related optic neuropathy." (PMID 39564550, 2024). "Although probably very uncommon, the possible involvement of AFG3L2 and SPG7 in optic neuropathies should prompt the screening of these genes in isolated and syndromic DOA patients, negative for OPA1 and OPA3 mutation." (PMID 26539208, 2015). "This variant is localized in the ATPase domain of the AFG3L2 clustered in the ATPase domain with other pathogenetic variants causing alteration of OPA1 processing and associated with optic neuropathy, presenting clinical features nearly indistinguishable from OPA1-related DOA." (PMID 39564550, 2024).
ptosis (4 papers, 2011 to 2025). The drooping of the upper eyelid. "A rare compound heterozygous mutations of AFG3L2, Y616C [c.1847A > G], and V723M [c.2167G > A] caused ptosis in his son as well as his asymptomatic single heterozygous mutated mother." (PMID 38012514, 2024). "A novel heterozygous partial AFG3L2 deletion of exons 14 to 16 was reported to cause loss of cerebellar function with ptosis." (PMID 38012514, 2024). "Ptosis and ophthalmoparesis may also be seen in some of the autosomal dominant spinocerebellar ataxias (SCAs), particularly SCA28, which is caused by mutations in the AFG3L2 gene." (PMID 28769865, 2017).
cerebellar degeneration (3 papers, 2011 to 2023). Degeneration of the cerebellum. "Of particular interest, double mutant Spg7-/-Afg3l2+/- mice exhibit a unique phenotype with severe early-onset spasticity and impairment of cerebellar function that is associated with axonal and cerebellar degeneration." (PMID 22022284, 2011). "Our patients' features closely resemble those of the Afg3l2+/-Spg7-/- mice -- early-onset axonopathy and cerebellar degeneration, as well as mitochondrial DNA depletion." (PMID 22022284, 2011). "For example, the dysregulation of mitochondrial electron transport chain activity was observed in SCA1 mouse cerebella and mutations in AFG3L2 encoding AFG3-like AAA ATPase 2 and might result in mitochondrial function abnormal and subsequently cerebellar degeneration." (PMID 37626842, 2023).
dominant optic atrophy (3 papers, 2015 to 2024). "Mutations in genes associated with mitochondrial fusion, including OPA1, AFG3L2, and MIEF1, lead to autosomal dominant optic atrophies (DOAs), specifically optic atrophy 1 (OPA1), optic atrophy 12 (OPA12), and optic atrophy 14 (OPA14), respectively." (PMID 39201313, 2024).
Atrophy (2 papers, 2022). Any weakening or degeneration, especially through lack of use. "The heterozygous AFG3L2 mouse recapitulated some pathological features of SCA28, including cerebellar atrophy, dark degeneration of Purkinje cells, and mitochondrial dysfunction." (PMID 36389399, 2022).
Cerebellar atrophy (2 papers, 2020 to 2022). Cerebellar atrophy is defined as a cerebellum with initially normal structures, in a posterior fossa with normal size, which displays enlarged fissures (interfolial spaces) in comparison to the foliae secondary to loss of tissue. "Mutations in the proteolytic domain of AFG3L2 cause dominant SCA28 and the rare recessive SPAX5, whose main clinical features are gait ataxia and lack of balance with cerebellar atrophy." (PMID 32600459, 2020).
Dystonia (2 papers, 2011 to 2025). An abnormally increased muscular tone that causes fixed abnormal postures. "Dystonia was previously observed in a family whose affected members carried an 18p chromosomal deletion that included AFG3L2, and Afg3l2+/-Spg7-/- mice also exhibited dystonic features." (PMID 22022284, 2011).
epilepsy (2 papers, 2019 to 2024). A brain disorder characterized by episodes of abnormally increased neuronal discharge resulting in transient episodes of sensory or motor neurological dysfunction, or psychic dysfunction. "AFG3L2, which encodes one of the subunits of the m‐AAA protease, is mutated in spinocerebellar ataxia SCA28 and in infantile syndromes characterized by spastic‐ataxia, epilepsy and premature death." (PMID 30989755, 2019).
Spastic Paraplegia 7 (2 papers, 2015 to 2026). "We recently provided evidence for non-Mendelian inheritance in spastic paraplegia 7 (SPG7), as heterozygous carriers of SPG7 mutations often also carried mutations in other disease-related genes, including AFG3L2, more frequently than expected by chance." (PMID 41877227, 2026).
autosomal recessive cerebellar ataxia (1 paper, 2024). "Strupp laboratory categorizes the phenotypic expressions of autosomal recessive cerebellar ataxias (ARCAs) into six categories but AFG3L2 related SPAX5 falls under metabolic or mitochondrial syndrome." (PMID 38012514, 2024).
color vision disorder (1 paper, 2022). The absence of or defect in the perception of colors. "Similar to patients with DOA caused by mutations in the ATPase domain of AFG3L2 and other genes, our patients also developed the disease in childhood, presenting with decreased visual acuity, impaired visual field, color vision disorder, pale optic disc, and thinning of RNFL." (PMID 35970831, 2022).
colorectal cancer (1 paper, 2025). A primary or metastatic malignant neoplasm that affects the colon or rectum. "CRABP2 plays a dual role in colorectal cancer: it promotes proliferation and suppresses apoptosis through the nuclear CRABP2/RB1 axis and the cytoplasmic AFG3L2/SLC25A39 axis." (PMID 40305785, 2025).
Dyschromatopsia (1 paper, 2024). A form of colorblindness in which only two of the three fundamental colors can be distinguished due to a lack of one of the retinal cone pigments. "c.1402C > T R468C in AFG3L2 was identified as a novel mutation in two patients in a family from two generations who additionally had dyschromatopsia but no sign of either SCA28 or SPAX5." (PMID 38012514, 2024).
Gillespie Syndrome (1 paper, 2024). "In fact, genes linked to autosomal-dominant ataxia have also recently been found to cause autosomal-recessive ataxia in cases of biallelic inheritance (e.g., AFG3L2/SPAX5, SPTBN2/SPARCA1, ITPR1/Gillespie Syndrome, and OPA1/Syndromic DOA or Behr phenotype)." (PMID 38391932, 2024).
idiopathic dystonia (1 paper, 2021). "Seven (10%) patients had confirmed genetic diagnosis (including THAP1, ADCY5, VPS41, ATXN3, AFG3L2, KMT2B), 12 (18%) had acquired causes and the remainder had idiopathic dystonia." (PMID 34437382, 2021).
Insulin resistance (1 paper, 2024). Increased resistance towards insulin, that is, diminished effectiveness of insulin in reducing blood glucose levels. "Only the mitochondrial processing peptidase miPEP and the ATP-dependent proteases PIRTM1 and AFG3L2 were downregulated across all insulin resistance models." (PMID 38960128, 2024).
Intellectual disability (1 paper, 2015). "Nevertheless, we suggest that genetically unresolved DOA patients with or without intellectual disability could be screened for the presence of an AFG3L2 mutation." (PMID 26539208, 2015).
liver cancer (1 paper, 2023). An epithelial or non-epithelial malignant neoplasm that arises from the liver. "Consistently, AFG3L2 knockdown indeed sensitized liver cancer cell to copper-induced cell death." (PMID 37277863, 2023).
lung adenocarcinoma (1 paper, 2026). A carcinoma that arises from the lung and is characterized by the presence of malignant glandular epithelial cells. "Reduced AFG3L2 expression in lung adenocarcinoma stabilizes SLC25A39 and enhances oxidative phosphorylation (OXPHOS) and ROS handling, thereby promoting tumor progression." (PMID 41599057, 2026).
MELAS (1 paper, 2017). "The levels of LONP1 were increased in all mutant cybrid lines with exception of m.Trp cells, expression of AFG3L2 was induced in all disease cell models except MELAS, and the levels of CLPP were increased in MELAS, m.Val and m.ND6 cells, whereas they were reduced in MERRF and m.Trp cells." (PMID 28740091, 2017).
myocardial infarction (1 paper, 2024). Gross necrosis of the myocardium, as a result of interruption of the blood supply to the area, as in coronary thrombosis. "To date, one epigenetic case study on monozygotic twins has revealed that hypomethylation of AFG3L2 in one of the twins maintains health while changes in methylation at multiple loci of AFG3L2 called as differential methylation on the other caused myocardial infarction." (PMID 38012514, 2024).
Myoclonus (1 paper, 2015). Very brief, involuntary random muscular contractions occurring at rest, in response to sensory stimuli, or accompanying voluntary movements. "The p.Gly116Arg variant in AFG3L2 may be a candidate for myoclonus, but we cannot exclude this is an initial symptom that will evolve into a more complex phenotype." (PMID 25927548, 2015). "Clinical re-evaluation of the patients confirmed some typical feature of AOA2 and identified a fourth sibling carrying p.Gly116Arg with initial signs of myoclonus, suggesting variants in AFG3L2 may be also associated with myoclonus." (PMID 25927548, 2015). "Because the same genotype was described in six cases from a Tunisian family with a typical AOA2 without myoclonus, we speculate this latter feature is associated with a second mutated gene, namely AFG3L2 (p.Gly116Arg variant)." (PMID 25927548, 2015).
myotonic dystrophy type 1 (1 paper, 2025). Steinert disease, also known as myotonic dystrophy type 1, is a muscle disease characterized by myotonia and by multiorgan damage that combines various degrees of muscle weakness, arrhythmia and/or cardiac conduction disorders, cataract, endocrine damage, sleep disorders and baldness. "Ceftriaxone has also been shown effective in decreasing post‐synaptic calcium levels in PNs and improving the motor phenotype of the Afg3l2+/− mouse (SCA28 model) and a myotonic dystrophy type 1 (DM1) model." (PMID 40464291, 2025).
neuropathies (1 paper, 2016). "In humans, loss of function mutations in either AFG3L2 or paraplegin lead to neuropathies associated with mitochondrial dysfunctions such as reduced complex I activity due to defective complex assembly." (PMID 27705926, 2016).
Salmonella Infections (1 paper, 2022). Infections with bacteria of the genus SALMONELLA. "We then measured the expression of various markers of the UPRmt, including the mitochondrial chaperone heat shock protein 60 and the mitochondrial proteases AFG3L2 and LONP1,24,27,28 in the presence or absence of Salmonella infection." (PMID 36516750, 2022).
schizophrenia (1 paper, 2016). A major psychotic disorder characterized by abnormalities in the perception or expression of reality. "Of the genes with significantly lower expression in males with schizophrenia, several were related to energy metabolism (ATP5B, ATP5A1, MRPL23, AFG3L2, ABCG2)." (PMID 26818902, 2016).
Sepsis (1 paper, 2025). Sepsis is defined as life-threatening organ dysfunction caused by a dysregulated host response to infection. "Our team found that the expression levels of ACADVL, AFG3L2, ETFB, PCCB, and PCK2 were significantly overexpressed in ARDS samples compared to sepsis samples (all P value < .05), which was consistent with the results of bioinformatics analysis." (PMID 40068062, 2025).
tauopathy (1 paper, 2021). Neurodegenerative disorders involving deposition of abnormal tau protein isoforms (tau proteins) in neurons and glial cells in the brain. "Furthermore, the loss of mitochondrial proteins, such as the protease AFG3L2 and the ROS scavenger SOD2, is associated with pTau presence, indicating that mitochondrial dysfunction promotes tauopathy in the brain." (PMID 34295920, 2021).
viral infection (1 paper, 2026). "The simplest explanation for this observation is that AFG3L2 does not proteolytically degrade activated VISA, which has been shown to form large insoluble polymers/aggregates upon viral infection." (PMID 41599057, 2026).
neurodegenerative disease (6 papers, 2010 to 2025). A disorder of the central nervous system characterized by gradual and progressive loss of neural tissue and neurologic function. "This study widens the clinical spectrum of neurodegenerative diseases caused by AFG3L2 mutations, which shall be considered as genetic cause of ADOA." (PMID 32600459, 2020). "The discovery that both paraplegin and AFG3L2 are implicated in human neurodegenerative diseases has sparked increasing interest in the m-AAA protease." (PMID 27911893, 2016). "This is in line with the fact that mutations in AFG3L2 or SPG7 lead to distinct neurodegenerative diseases, characterized by a pure neuronal and axonal phenotype, respectively." (PMID 27911893, 2016). "The importance of AFG3L2 in maintaining cellular protein function is underscored by the recent observation that mutations in this protein cause the neurodegenerative disease SCA28." (PMID 22916034, 2012). "They include those encoding eukaryotic translation initiation, elongation and translation factors, and genes that have been previously associated with other neurodegenerative diseases, like the ATP-ase family gene 3-like 2 (AFG3L2) and ubiquitin-like modifier activating enzyme 1 (UBA1)." (PMID 21915392, 2011).